CD4 (CD4 molecule)
Diseases named in the same sentence as CD4 in open-access papers (continued):
Sharing a sentence is not in itself a finding about the gene and the disease.
tumor (continued). "Conversely, the Tregs subset of CD3+CD4+ lymphocytes, N2 neutrophils, M2 macrophages and MDSCs can promote carcinogenesis and facilitate tumour immune escape from immune destruction." (PMID 36980527, 2023). "In a study using a hepatocellular carcinoma model, tumor-infiltrating CD4+ T cells responded to a VEGFR-2 blockade by increasing the PD-1 expression levels and further inhibiting CTL function." (PMID 37631236, 2023). "Generally, CD8+ cytotoxic T cells and T helper 1 (Th1) CD4+ T cells promote anti-tumor immunity, while regulatory CD4+ T cells (Treg) and T helper 2 (Th2) CD4+ T cells are associated with immune evasion." (PMID 37190322, 2023). "Meanwhile, other immune cells, including CD4+ T cells, monocytes and neutrophiles all had similar presence in tumor tissues among WT and Gpr68-/- mice, in both males and female." (PMID 37350933, 2023). "T lymphocytes are the major subgroup of tumor-infiltrating immune cells, among which CD8+ T cells and CD4+ T cells comprise the primary immune cells responsible for anti-tumor immunity." (PMID 37593099, 2023). "Studies have demonstrated that B cells activate CD4+ T cells, resulting in the accumulation of T cells in the tumour microenvironment and the differentiation of CD4+ and CD8+ T cells into distinct phenotypes." (PMID 38137361, 2023). "CD4 T cells are necessary for tumor control in vivo, as shown by the in vivo T-cell depletion experiments." (PMID 37185301, 2023). "Studies have demonstrated tumor neoantigen released from the ablation bed yielded more effective dendritic cells in inducing CD4+ and CD8+ T cells." (PMID 36969248, 2023). "S15+ tumor cells or TAMs were spatially closer to CD4+FoxP3+ Tregs than S15− tumor cells or TAMs, both in the PD-L1− or PD-L1+ tumor cells or TAMs." (PMID 37674198, 2023). "For example, estrogen inhibits both the proliferation of CD4+ T-cells and the activities of natural killer (NK) and cytotoxic T lymphocytes (CTLs) to contribute to promoting an immunosuppressive tumor microenvironment." (PMID 37958417, 2023). "Further analysis revealed that the expression of BIRC5 was negatively correlated with infiltrating levels of B cells, CD4+ T cells and dendritic cells in the tumor microenvironment of LUAD (p < 0.05)." (PMID 37834111, 2023). "Observation of the tumor section by immunofluorescence staining further confirmed the most enrichment of tumor‐infiltrating CD4+ T cells and CD8+ T cells after sgCas9‐AdV/Gel treatment." (PMID 36840638, 2023). "Supplementation with A. muciniphila increased the recruitment of CCR9 + CXCR3 + CD4+ T lymphocytes into mouse tumor beds in an IL-12-dependent way." (PMID 37111034, 2023). "In the majority of patients tested by FACS (78%) TMEM123 had a higher expression in tumor-infiltrating CD8+ than in CD4+." (PMID 37426665, 2023). "The Lm-GP61 vaccine developed using the CD4+ T cell epitopes can impede tumor progression by inducing TH1 and CTL responses, synergizing PD-L1 blockade to mediate tumor suppression." (PMID 37868979, 2023). "We provide evidence that IFN-γ acted directly on tumor cells to promote apoptosis and that tumor sensitivity to the pro-apoptotic effects of IFN-γ is a major determinant of CD4+ CAR T-cell efficacy." (PMID 37248395, 2023). "Tumoural PD-L1 expression and CD4+/CD8+ tumour-infiltrating lymphocytes were evaluated in human GBM specimens." (PMID 37370741, 2023). "In this context, the peptides sharing with the CD8+ T cells trigger the cytotoxic reaction while exposure to CD4+ T cells determines antibody production against the tumor cells." (PMID 36900152, 2023). "HLA-DR is associated with CD68 in primary GBM, and with CD4 in recurrent GBM, suggesting a switch between activation of M1-like macrophages and T-cell activation during tumor progression." (PMID 37370866, 2023).
tumor (continued). "Along these lines, the relevance of an immunoscore has already been recognized in other histologies, and an exhausted immune profile and low CD3/CD4 T cells in the tumor center are likely related to shorter survival in iCCA patients." (PMID 37626908, 2023). "Immune cells are also affected by environmental factors, for example, more acidic pH (often due to an increase in lactate) in the TME inhibits mobility and tumor infiltration of both CD4 and CD8 T cells." (PMID 37020875, 2023). "The percentages of tumor-infiltrating CD4 and CD8 T cells as well as interferon (IFN)-γ and granzyme B (GZB) secretion were higher in the methionine-treated group than in the PBS-treated group." (PMID 37147330, 2023). "Tumor-reactive CD4+ T cells have been found to ensure efficient effector CD8+ T cells recruitment at the tumor site." (PMID 37516867, 2023). "This impairs the anticancer/tumor action of tumor infiltrating CD4+ and CD8+ T cells in the pro-inflammatory environment." (PMID 37275901, 2023). "Compared with the control group, the percentage of IFN-γ+ CD4+ or IFN-γ+ CD8+ T cells was significantly increased in tumor after treatment with either OX40 antibody, and the level of increase was similar between these two antibodies." (PMID 37576888, 2023). "Overall, high proportions of monocytes and memory resting CD4+ T cells were infiltrated in normal tissues, whereas the types of immune cells infiltrated in tumor tissues were diverse." (PMID 37280525, 2023). "CD4+ T cells, as a type of helper T lymphocytes, recognise soluble antigens secreted by tumour cells and participate in the activation of B cells, cytotoxic T cells, macrophages and NK cells, thus, increasing and expanding the immune response." (PMID 37767473, 2023). "Samples were grouped according to DDR1 expression (low, <50% vs. high, ≥50% or low, <25% vs. high, ≥75%) and were compared to FoxP3, a nuclear transcription factor present in Tregs that represents the main tumor-promoting CD4+ T-cell population." (PMID 38136314, 2023). "CD4+ helper T cells (Th cells) are essential effector cells for eliciting a potent anti-tumor immune response." (PMID 36939853, 2023). "CD4+ and CD8+ T-cells can exert effector function and regulate tumor growth and are typically associated with good prognosis." (PMID 37638000, 2023). "CD4+ memory T cells are essential for effectively controlling immune function, including tumor immunosurveillance, and positively impacting the prognosis of patients with CESC." (PMID 38087815, 2023). "Long-term tumor-specific cytotoxic T lymphocyte activity maintenance requires class II antigen-reactive CD4+ T cells." (PMID 37881436, 2023). "This led to activation of the CXCL10-CXCR3 chemotactic chemokine axis and promotion of an antitumor immune response, while suppressing the tumor-promoting FoxP3+ CD4+ T cells." (PMID 37035245, 2023). "On the other hand, SEMA3A secreted by a variety of human tumor cells (lung, breast, prostate, glioblastoma, and colorectal cancer cells) has been shown to inhibit tumor-CD4+/CD8+ lymphocyte interactions and T-cell activation and proliferation." (PMID 38067240, 2023). "Using Reactome for pathway enrichment analyses, we observed Trp2Vax and immunotherapy treatment upregulated the IL-12 responsive genes, including ITGB1, SOCS3, IFNG and STAT4 in the tumor-infiltrating CD4+ T cells (with a False Discovery Rate, FDR= 0.0016)." (PMID 36911698, 2023). "We found increased infiltration of CD8+ and CD4+ T cells in the tumor and systemically in the spleen." (PMID 36757811, 2023). "Fucosylation of the major histocompatibility complex-II HLA-DRB1 enhances CD4+ T cell immunity and enhances anti-PD-1 efficacy in a murine tumor model." (PMID 37388743, 2023). "Immunohistochemistry analysis of the tumors revealed a massive tumor infiltration by NK cells and leukocytes and a mild increase in CD4+ T cells." (PMID 36839658, 2023).
tumor (continued). "PITPNM3 knockdown with CD4-aptamer-PITPNM3-siRNA chimeras in naive CD4+ T cells in a humanized mouse tumor model significantly attenuated primary tumor cell survival in situ and lung metastasis by promoting antitumor immunity." (PMID 36418470, 2023). "Treg and Th2 cells are derived from CD4 differentiation induced by tumor microenvironmental signals, such as tumor antigens, cytokines (such as TGF-β), and other soluble molecules, and have strong immunosuppressive, antitumor immunity inhibitory function." (PMID 37568713, 2023). "In the tumor-draining lymph nodes, CD4+ T cell depletion or its combination with PD-L1 blockade therapy significantly elevated the proportions of CD44+CD69+CD8+, as well as central memory CD44+CD62L+CD8+ and effector memory CD44+CD62L−CD8+ T cells." (PMID 36969495, 2023). "The IL-1 (β in humans, α in mice) activated the NLRP3 Inflammasome in the tumor microenvironment and induced IL-22 production in various CD4+ T-cells including Th22, Th17, and Th1 cells." (PMID 37835465, 2023). "At the same time surgery of the primary tumor led to the rebound of antibody and cell-mediated response, restoring immunocompetence and increasing CD4 and CD8 cells in mice with metastatic BC." (PMID 36793604, 2023). "Meanwhile, the C2 subtype promoted tumor progression and immune suppression and was characterized by high percentages of resting CD4+ T cell memory, M2 macrophages, resting DC cells, resting mast cells, and neutrophils." (PMID 37540227, 2023). "The results from immunofluorescence staining suggested that the frequency of CD4+ T helper cells infiltrating into distant tumor in the FKPN plus irradiation group was significantly increased." (PMID 37031242, 2023). "CD8+ T cells possess the ability to play a crucial function in the eradication of malignant cells and CD4+ T cells primarily function as immune memory and immune protection during tumor metastasis." (PMID 37904179, 2023). "In contrast with the MHC-I, tumor-specific antigens of B-cell lymphomas presented by MHC-II are recognized by CD4+ T cells." (PMID 36765793, 2023). "Interventions in ER Ca2+ signaling in CD4+ T cells have been postulated as a strategy for rehabilitating the tumor microenvironment’s immunological activity." (PMID 36824126, 2023). "Tumor-associated macrophages and neutrophils possess immune-suppressive abilities, whereas dendritic cells, CD8+T cells, CD4+T cells, NK cells, etc., are frequent immune-activating cells." (PMID 37404826, 2023). "While CD8+ T cells promote a tumor-suppressive environment, CD4+ T cells have a tumor-promoting effect." (PMID 36836239, 2023). "We show our REP TIL protocol favors the expansion of CD4+ T cells, which originate from small T cell clones in the tumor microenvironment (TME)." (PMID 37484198, 2023). "The investigation of GITR in Tregs as a potential target has revealed that the use of antibodies can facilitate the transformation of Tregs into CD4 + T cells, thereby diminishing their inhibitory impact on tumor immunity." (PMID 38089966, 2023). "Because CD4 T cells see their target ligands naturally through presentation by HLA class II molecules, they can only naturally recognize tumor cells that are HLA class II positive." (PMID 37810959, 2023). "TM4SF1+, SOX4+, and MKI67+ tumor cells; CXCL12+ cancer-associated fibroblasts; CD4+ resident memory T cells; Treg; IgA+ plasma cells; and several myeloid subsets were enriched in stage IV CRC, most of which were associated with overall survival of patients." (PMID 37360193, 2023). "The combination therapy increased the infiltration of CD8+ T cells, and the percentages of IFNγ+, TNFα+ CD8+ T cells and the percentages of IFNγ+, TNFα+ CD4+ T cells in the tumor microenvironment." (PMID 37553341, 2023). "All together, we conclude that tumor-infiltrating DC317, the mature DC in the IL-32hi TME34 and the tumor-infiltrating DC_S318 are most likely derived from cDC1 and appear to reflect conditions of CD4+ T-cell help." (PMID 36639382, 2023).
tumor (continued). "Our data showed that FOXP3+ expression was frequently observed in tumor and peri-tumoral compartments, suggesting that regulatory CD4+ lymphocytes had a greater tendency to infiltrate tumoral parenchyma." (PMID 37366900, 2023). "The CD4+ effector T cells preferentially cluster at tumour invasive margins where they interact with MHC-II+CD11c+ antigen-presenting cells." (PMID 37316667, 2023). "CD8+ T cells are an important part of the tumor immune response and play an important role in killing cancer cells, while CD4+ T cells mainly play a role in regulating the tumor immune response." (PMID 38259481, 2023). "Specifically, activation of parasympathetic nerves can downregulate the expression of programmed cell death protein-1 (PD-1) on CD4+ tumor-infiltrating T-lymphocytes, and improve the expression of interferon-γ, thus enhancing anti-tumor immunity." (PMID 37371563, 2023). "CAF subsets with distinct extracellular matrix (ECM) programs are associated with T cell exclusion from the tumor and correlate with PD-1+ and CTLA4+ CD4+ T cell content in tumor lesions." (PMID 37086273, 2023). "CD4 + T cells, mainly including CD4 + T-helper (Th) cells and Tregs, are also crucial in tumor immunity." (PMID 36773210, 2023). "Our results indicated that CD4 T cells, M0 macrophages, AC-MCs, and activated DCs were increased, but the Tregs and resting MCs were decreased in tumor tissue." (PMID 36644231, 2023). "The tumor immune microenvironment (TIME) comprises abundant activated effector cytotoxic CD8+ and helper CD4+ tumor-infiltrating lymphocytes (TILs)." (PMID 37264091, 2023). "In HLA-DR+ melanoma, MHC II lessens CD8+ T cell activity by inducing LAG3+ and FCRL6+ TILs or recruiting CD4+ T cells to the tumor." (PMID 37841280, 2023). "Because of the induction of tumor-specific CD4 + and CD8 + T cells, significant tumor reduction can be induced in colon cancer mouse models." (PMID 37381018, 2023). "Densities and percentages of CD8+ T cells, CD4+ T cells, FoxP3+ T cells, CD20+ B cells, M1 and M2 tumor-associated macrophages and NK cells (CD56dim and CD56bright) were quantified." (PMID 36969032, 2023). "More specifically, we assessed the effect of different APC-binding molecules on their ability to elicit neoepitope-specific CD8+ and CD4+ T-cell responses and to improve anti-tumor efficacy." (PMID 37720215, 2023). "It is worth noting that S15+ tumor cells were closer proximity to CD4+FoxP3+ Tregs compared with S15− tumor cells." (PMID 37674198, 2023). "Although CD8+ CAR T cells dominated early on, the CD4+ CAR T cells eventually took over and were associated with long-term tumor control." (PMID 37654482, 2023). "In contrast, the combination of N1, FSL-1, R848, and anti-CTLA4 (TheraVacplus) further increased tumor-infiltrating leucocytes, CD4+ T cells and CD8+ T cells, effector/memory T cells, and markedly lowered fractions of tumor-infiltrating cDCs and pDCs." (PMID 37190294, 2023). "In our in vivo experiments, CD4 CAR-T cells have shown to be extremely efficient in counteracting tumor growth when administered as a single agent, while CD8 CAR-T cells alone have been ineffective in most cases." (PMID 36593069, 2023). "Meanwhile, it has also been reported that blocking TGF‐β signaling, such as TGF‐β receptor II (TGF‐βRII), in CD4+ T cells mediates tumor regression by promoting the remodeling of the blood vasculature, which means a mature and organized tumor vasculature." (PMID 37829505, 2023). "Overall, this analysis showed that tumor infiltrating CD4 + FoxP3 + T-cells co-expressed most of our ICPs of interest." (PMID 38057799, 2023). "Several studies attempted to analyze the tumor microenvironment (TME) of sarcomas, including the composition of the tumor infiltrating CD4+ and CD8+ T cells, tumor-associated macrophages (TAM), and dendritic cells." (PMID 37298520, 2023).
tumor (continued). "Analysis of tumor tissue from mice treated with BI 764532 revealed infiltration of CD3 + T cells into tumor tissue, including increased numbers of both CD4 + and CD8 + T cells within tumors compared with the vehicle-only controls." (PMID 37355629, 2023). "Transcriptomic analysis of tumor-specific CD4+ T cells revealed a type I IFN response signature with an upregulated exhaustion signature characterized by increased PD-1 levels." (PMID 37304294, 2023). "We found that reduced H3K79 methylation in tumor-infiltrated CD4 T cells reduced AMPK expression and consequently increased PD-1 expression." (PMID 37147330, 2023). "T cell types of NK cells, CD8 + cells and CD4 + cells were detected in all three zones, with the exception of CD8 + cluster 7 and CD4 + cluster 8 mainly presenting in tumor zone." (PMID 37644609, 2023). "In this study, LCN2 was screened for the first time as a key DEP in tumor-infiltrating T cells, particularly in CD4+ T cells." (PMID 38072118, 2023). "TME is mainly composed of T cells (CD4 helper, CD8 cytotoxic and regulatory) and tumor-associated macrophages (TAMs), but the impact of these cells on the natural course of the disease is not absolutely understood." (PMID 37372147, 2023). "Multiplex immunofluorescence images from reporter mouse spleen and B78 tumor illustrate mCherry-expression by several subsets of immune cells including CD4+mCherry+ (yellow arrow) and CD8+mCherry+ (magenta arrow) T cells as well as other immune cells." (PMID 37020875, 2023). "Higher B cell infiltration and B cell receptor (BCR) diversity allows presentation of diverse tumor antigens by B cells, resulting in activation of follicular helper CD4 T cells (Tfh) and tumor reactive CD8 T cells after ICI therapy." (PMID 37435085, 2023). "An increase in ID8 tumor-specific recall responses was also seen from CD4+ T cells isolated from the peritoneal lavage fluid of OrfV-treated mice but not control animals, based on the increased expression of IFN-γ and IFN-γ and TNF-α." (PMID 38075247, 2023). "An increase in CD4+ T cell infiltration, and reduced tumour vessel diameter and endothelial proliferation, followed by delayed tumour growth, were observed." (PMID 37403792, 2023). "The efficacy of Mut_48 is thus related to presentation of the CD4+ T cell helper antigen alongside a tumor-specific CTL NeoAg most likely by the same APC, mechanistically consistent with Th-mediated ‘licensing’ of APC to program optimal CD8+ T cell responses." (PMID 37655661, 2023). "In fact, several studies demonstrated Eomes and T-bet co-expression in tumor-reactive CD4+ CTL, thereby emphasizing the link between cytotoxic and Th1 differentiation programs." (PMID 37965314, 2023). "The tumor core and inner invasive margin of primary tumors and lung metastases have higher lymphocyte infiltration (CD4 and CD8 T cells, B cells, and γδ T cells) than in liver and peritoneal metastases." (PMID 37768208, 2023). "Antitumor CD8+ and CD4+ T cells can identify tumor cells through the recognition of peptide antigens presented by human leukocyte antigen class I (HLA-I) and class II (HLA-II) cell surface molecules, respectively." (PMID 37142057, 2023). "Our findings reveal that NaHCO3 or the combination of NaHCO3 with anti-PD-L1 therapy lead to a significant increase in CD8+ and CD4+ T cell infiltration in tumor tissues." (PMID 37894298, 2023). "Here, tumor size correlated better with the percentage of activated or resident T helper cells of all live cells (CD4 + CD69 +)." (PMID 37118819, 2023). "In LUSC, MEX3A was similarly shown to be positively correlated with tumour purity and B cells and negatively correlated with CD4+ T cells." (PMID 36507941, 2023). "In comparison to the untreated or abscopal effect group, the mice presenting significant abscopal effect also elevated the proportion of CD4+ TNF-α+ T cells into the tumor." (PMID 37182153, 2023).